INS (insulin)
Diseases named in the same sentence as INS in open-access papers (continued):
Sharing a sentence is not in itself a finding about the gene and the disease.
type 2 diabetes (continued). "Monitoring of sleep duration may serve as a useful tool for identifying high-risk people with type 2 diabetes in clinical practice for possible intervention, especially for those being treated with both oral glucose-lowering drugs and insulin." (PMID 32671413, 2020). "Treatment of type-2 diabetes with insulin sensitizing drugs lowers the risk of PD." (PMID 35224554, 2020). "Non-insulin-dependent type 2 diabetes mellitus (T2D) is a heterogeneous disorder caused by the dysfunction of insulin-producing beta-cells, resulting in impaired insulin secretion or increased insulin resistance in response to glucose in skeletal muscle, hepatic system, and adipose tissue." (PMID 33905469, 2020). "However, the Prescribed Drugs Register captures all insulin dispensed at Swedish pharmacies and the strong association with insulin-treated type 2 diabetes supports a true association between pubertal timing and type 2 diabetes." (PMID 32201902, 2020). "Type 2 diabetes (T2D) is characterized by hyperglycemia, hyperlipidemia, and key changes in amino acid profiles that are associated with alterations in peripheral insulin sensitivity and β-cell function." (PMID 33457426, 2020). "Insulin degludec and glargine U300 have been shown to be associated with a lower risk of hypoglycaemia, at equivalent glycaemic control compared with glargine U100 in individuals with type 2 diabetes." (PMID 31984443, 2020). "It is argued that meals that lead to persistent high postprandial serum concentrations of insulin and triglycerides (i.e. remained elevated at the set time points) are unhealthy and most likely increasing the risk of development of type 2 diabetes and cardiovascular diseases." (PMID 32366255, 2020). "This poor sleep quality may partly explain the results that sleep deprivation was associated with the highest mortality risk among individuals with type 2 diabetes using both insulin and oral glucose-lowering medication." (PMID 32671413, 2020). "Furthermore, type 2 diabetes predisposing variants in genes involved in the insulin signalling pathway are expected to have an opposing direction of effect on cancer." (PMID 32705315, 2020). "However, after type-2 diabetes develops, some individuals develop progressive beta-cell dysfunction and failure associated with a decrease in fasting insulin." (PMID 32153503, 2020). "However, insulin resistance in target tissues and deficiency of insulin secretion from pancreatic β-cells are the main characteristics of type 2 diabetes." (PMID 32927596, 2020). "When comparing individuals carrying ≥ 17 alleles that raise fasting insulin levels with those exhibiting genetically determined low fasting insulin levels, an increased risk of elevated blood pressure, cardiovascular disease, and type 2 diabetes was observed." (PMID 32819363, 2020). "Interestingly, another study found a common variant of TFB1M to be associated with reduced insulin secretion and increased risk of type 2 diabetes in Tfb1m-deficient mice." (PMID 32765591, 2020). "Indeed, studies have shown that type 2 diabetes risk alleles, which have been shown to be associated with reduced insulin secretion and beta cell dysfunction, were related to lower birth weight." (PMID 33490284, 2020). "Lastly, insulin carries the highest hypoglycemic risk; however, if adjustments are made (e.g., once-daily basal insulin with morning application) and assistance is provided, insulin can be a sensible choice in older patients with type 2 diabetes." (PMID 32741836, 2020). "In an experimental study where slow wave sleep (SWS) was selectively disturbed, insulin sensitivity was decreased after three nights of intervention, which suggests that reduced sleep quality may contribute to an increase in the risk of type 2 diabetes." (PMID 32549208, 2020). "This lower insulin clearance can explain the hyperinsulinemia of African Americans (adults and children), which may contribute to the higher risk of Type 2 diabetes in those individuals." (PMID 33658981, 2020).
type 2 diabetes (continued). "In other words, the GLR and PLR results in this study might be associated with the risk of type 2 diabetes, as demonstrated by the glucose-related markers (insulin, HOMA-IR, and adiponectin) measured in the present study." (PMID 32346379, 2020). "Therefore, the aim of this study was to explore the association of 1,5-anhydroglucitol with acute insulin response to arginine among patients with type 2 diabetes." (PMID 32775460, 2020). "The lack of association between MBA and HOMA-IR as well as fasting insulin could potentially explain the missing link to type 2 diabetes development." (PMID 32690629, 2020). "Associations between offspring birth weight and fathers' risk of type 2 diabetes strengthen the fetal insulin hypothesis, as fathers can only directly affect offspring fetal growth through inherited fetal genes." (PMID 33490284, 2020). "Notably, an observational study indicated that metformin added to initial continuous subcutaneous insulin infusion or multiple daily injections decreased glucose fluctuation and nocturnal hypoglycemic risk in patients with type 2 diabetes." (PMID 32622354, 2020). "Insulin signaling defects may result in the development of metabolic diseases, such as type 2 diabetes, and the InR mutant has been suggested to bear insulin signaling deficiency." (PMID 32664584, 2020). "In type 1 diabetes the cause is a total deficiency of insulin secretion, while in type 2 diabetes the cause is a combination of resistance to insulin action of the liver, skeletal muscle, and adipose tissue and an inadequate compensatory insulin secretory response." (PMID 32528413, 2020). "A diet deficient in magnesium, very common in western dietary patterns full of ultra-processed food, has been associated with an impaired cellular insulin-mediated glucose uptake and with a remarkably high risk of developing glucose intolerance and type 2 diabetes." (PMID 33396570, 2020). "Identification of new classes of genetic variants associated with type 1 diabetes may enhance the application of genetic risk scores in many ways, from prediction of risk to the need for insulin treatment in type 2 diabetes." (PMID 32797243, 2020). "Indeed, loss-of-function mutations in PTEN cause a rare cancer-predisposition syndrome and protect against type 2 diabetes (through enhanced insulin sensitivity)." (PMID 32705315, 2020). "Considering that KK‐Ay spontaneously showed the association between type 2 diabetes and hyperinsulinemia, the increased expression of megalin might have been related to insulin levels." (PMID 33098615, 2020). "An animal study showed that sleep deprivation of just one day may alter liver function involved in blood glucose and insulin control, increasing the risk of developing type 2 diabetes." (PMID 32549208, 2020). "Intensive insulin therapy has been shown to reduce the risk of microvascular complications in the short-term and macrovascular complications after 10 years of post-trial follow-up in newly diagnosed patients with type 2 diabetes (2, –4)." (PMID 31859911, 2020). "Reflecting the HCD-induced increased IR, analysis of pancreatic β-cell function revealed that it was accompanied by a compensatory hyper-production of insulin and glucagon, followed by islet death typical of the pancreatic failure associated with established Type-2 diabetes in humans." (PMID 32163524, 2020). "Several mtDNA (mitochondrial DNA) variations in human populations have been implicated in increased or decreased risk of type 2 diabetes while, in animal models, alterations in beta cell mtDNA led to reduced insulin secretion, hyperglycaemia and beta cell loss." (PMID 32894309, 2020). "In addition, both insulin treatment and metformin therapy are associated with sleep duration and quality in individuals with type 2 diabetes." (PMID 32671413, 2020).
type 2 diabetes (continued). "Changes in STARD10 expression in carriers of type 2 diabetes risk alleles may consequently affect the β-cell lipid composition and alter granule maturation and, ultimately, insulin synthesis and secretion." (PMID 32416313, 2020). "The potential to reduce glucose-lowering medications including insulin may ultimately also help lower the personal and societal costs associated with type 2 diabetes." (PMID 32193200, 2020). "The focus may identify a single key missing feedback signal such as the loss of insulin in type 1 diabetes or, more likely, may be a result from a number of factors as observed in type 2 diabetes." (PMID 32373557, 2020). "Moreover, it has an impact on lipids (increases HDL‐C and reduces triglycerides), improves insulin sensitivity, and modestly modifies body weight and fat mass, reducing the risk of developing type 2 diabetes." (PMID 32692414, 2020). "Many synthetic medicines like insulin and oral hypoglycemic drugs available on the market are used to treat type 2 diabetes, but the long term use of insulin therapy and oral synthetic medicines may cause severe side effects." (PMID 33322801, 2020). "Another strength of the current review is that it investigates individual cardiometabolic biomarkers (e.g., insulin sensitivity, fasting glucose, cardio-metabolic risk score) in addition to global measures of cardiovascular and metabolic health (e.g., type 2 diabetes, CVD)." (PMID 32563261, 2020). "“When I came, I found they can provide me meal and insulin injection regularly, and the risk of coma (due to hypoglycemia) could be prevented." (PMID 32762717, 2020). "Although impaired insulin action is a major risk factor for type 2 diabetes, the molecular mechanisms underlying this disorder remain unclear." (PMID 31557807, 2019). "A polymorphism in the pancreatic channel TALK1 causes a reduction in β-cell excitability and glucose-stimulated insulin secretion, which could explain increased type 2 diabetes susceptibility." (PMID 30770809, 2019). "Studies indicate that fat quality also may affect insulin sensitivity and hence, the risk of type 2 diabetes (T2D)." (PMID 31091649, 2019). "Type 1 as well as type 2 diabetes are characterized by a loss of insulin-producing β-cells." (PMID 31676778, 2019). "Consequently, dedifferentiation in type 2 diabetes causes the effective loss of functional β-cell mass (“true β-cells”) with the ultimately defective insulin secretion." (PMID 30450940, 2019). "Impaired insulin secretion from pancreatic islets is a hallmark of type 2 diabetes (T2D)." (PMID 31123324, 2019). "Type 2 diabetes-associated humoral factors, such as insulin, have skeletal effects." (PMID 31233501, 2019). "This could be comparable to studies on beta cell function in immigrants to Israel from Yemen; their insulin production was found to be insufficient for the new diet and lifestyle, causing high risk for type 2 diabetes." (PMID 30804889, 2019). "Cross-sectional studies in youths and adults showed that the shape of the OGTT glucose response curve could indicate insulin sensitivity and β-cell function, as well as differentiate type 2 diabetes risk." (PMID 31690291, 2019). "Our results showed that light change-simulated shift work altered insulin sensitivity during the light phase and shifted glucose tolerance rhythms in female mice, suggesting a causal association between long-term shift work and type 2 diabetes." (PMID 31851682, 2019). "Abnormal dietary fat intake directly contributes to a casual role in hepatic lipid accumulation, such as TG, cholesterol, and lipid droplets in the cytoplasm of hepatocytes, and lipotoxicity that is caused by fat accumulation induces hepatic insulin resistance in the pathogenesis of type 2 diabetes." (PMID 31277481, 2019).
type 2 diabetes (continued). "Patients with type 2 diabetes also have an increased risk of developing dementia, particularly vascular dementia and Alzheimer’s disease and it has been hypothesized that insulin resistance in the brain contributes to the development of Alzheimer’s disease." (PMID 31133864, 2019). "ARL15 played a role in type 2 diabetes susceptibility and fasting insulin regulation." (PMID 31623319, 2019). "While type 1 diabetes (T1D) is characterized by absolute insulin deficiency, type 2 diabetes (T2D) is characterized by insulin secretion insufficient to compensate for insulin resistance, stressing the importance of dysfunctional beta-cells also in the pathogenesis of T2D." (PMID 31467927, 2019). "As insulin resistance is the major hallmark of type 2 diabetes, impaired insulin action in the brain might engender cognitive impairment." (PMID 31675964, 2019). "Although information on hypoglycemic episode was not available in our samples, others have shown that the overall incidence of hypoglycemia requiring medical intervention among adults with type 2 diabetes is considerable, and is strongly linked with insulin use." (PMID 30768625, 2019). "For Type II diabetes in which β cells are still intact and functional, the presence of ROS may cause oxidative stress in the β cells, leading to lower levels of insulin secretion." (PMID 31510091, 2019). "If type 2 diabetes is associated with AD, then reduced insulin signaling might underlie AD, but why would hyperinsulinemia or insulin treatment of type 2 diabetes aggravate AD?" (PMID 30652125, 2019). "Total NEFA levels, fasting plasma PL FA profiles and an insulin sensitivity index (Si), derived from intravenous glucose tolerance minimal-model analysis, were available from 533 participants, all at elevated risk of type 2 diabetes." (PMID 32076549, 2019). "In addition to its association with type 2 diabetes, evidence also suggests DNA methylation is associated with insulin sensitivity measured by HOMA-IR." (PMID 30641161, 2019). "Besides, PTEN haploinsufficiency has been proved to be obesogenic but decrease the risk of type 2 diabetes (T2D) owing to enhanced insulin sensitivity." (PMID 31824561, 2019). "First, there exists the possibility that the use of insulin or glycemic control may have affected the results because of the association between inflammation and increased risk of type 2 diabetes." (PMID 31415573, 2019). "Pathologic conditions associated with type 2 diabetes (such as high blood glucose, inflammation, hypoxia, and fatty acids) can alter the quantity and components of ELVs secreted from the pancreas or peripheral insulin-targeting tissues." (PMID 30993115, 2019). "HLA-DRB1 was proved to increase insulin secretion and reduce the risk of type 2 diabetes." (PMID 31881887, 2019). "However, weight management in type 2 diabetes is complicated by the fact that commonly used pharmacological interventions, i.e. sulfonylureas and insulin treatment, are associated with weight gain." (PMID 31216324, 2019). "Increased concentrations of tumor necrosis factor (TNF)-α and interleukin (IL)-6 associated with obesity and type 2 diabetes might interfere with the anti-inflammatory effects of insulin, which can promote inflammation." (PMID 31504048, 2019). "In addition, we have shown ethnic differences in the associations between tissue-specific sites of insulin sensitivity, which adds to the concept of ethnic distinctions in type 2 diabetes pathophysiology." (PMID 30729259, 2019). "Epigenetic mechanisms regulate gene expression and may influence the pathogenesis of type 2 diabetes through the loss of insulin sensitivity." (PMID 30641161, 2019). "Our study shows that late-onset type 1 diabetes with severe endogenous insulin deficiency is relatively common (21% of insulin-treated patients) and has very similar characteristics to young-onset type 1 diabetes, but is frequently initially treated as type 2 diabetes." (PMID 30969375, 2019).
type 2 diabetes (continued). "However, some researchers have found that FS is associated with an increased incidence of type 2 diabetes, impairs insulin signaling, and worsens insulin resistance, inducing inflammatory responses by the NLRP3/caspase-1 pathway." (PMID 30939798, 2019). "Moreover, progressive loss of insulin secretory function is an inevitable result of the natural history of type 2 diabetes." (PMID 31467928, 2019). "Various studies have indicated an association between vitamin D deficiency and the development of type 2 diabetes and the metabolic syndrome, since a vitamin D deficiency (25(OH)D < 20 ng/mL) increases insulin resistance and reduces insulin secretion from beta cells in the pancreas." (PMID 31689953, 2019). "Type 2 diabetes and obesity are now widely listed among risk factors for developing AD, now increasingly recognized as a metabolic disease, since patients display impaired brain glucose metabolism and insulin signaling." (PMID 30770297, 2019). "However, patients predisposed to type-2 diabetes fail to secrete enough insulin to meet the metabolic demand (due to insulin resistance in several tissues) and type-2 diabetes occurs." (PMID 31178685, 2019). "An effect of high childhood BMI on insulin sensitivity and future risk of adult type 2 diabetes is supported by a recent finding from the Bogalusa Heart Study showing that childhood obesity precedes hyperinsulinemia and the development of type 2 diabetes in adult life." (PMID 30517677, 2019). "Various studies have indicated that a lack of vitamin D must be regarded as a pathogenic factor for type 2 diabetes and the metabolic syndrome, since a vitamin D deficiency (25(OH)D < 20 ng/mL) increases insulin resistance and reduces insulin secretion from beta cells in the pancreas." (PMID 31689953, 2019). "However, the associations of eating competence with new type 2 diabetes or insulin sensitivity were at least partly mediated by BMI." (PMID 31905938, 2019). "Type 2 diabetes is owing to IR, characterized by a deficient action of the peripheral tissues, including skeletal muscles, adipose tissues, and liver, in response to insulin." (PMID 31019978, 2019). "Insulin secretion is regulated by several hormones and neurotransmitters, and the diseases associated with this pathway are defects in the degradation of ganglioside and type II diabetes mellitus." (PMID 31323913, 2019). "The overarching goal of this research is to identify and validate molecules, pathways and ultimately new treatments that confer the benefits of exercise to improve insulin sensitivity, and attenuate the loss of skeletal muscle function with aging and type 2 diabetes." (PMID 31686269, 2019). "Type 2 diabetes is caused by relative insulin hyposecretion and insulin resistance." (PMID 31357734, 2019). "This led to the hypothesis that they have a thin-fat insulin-resistant phenotype, which increases their risk of type 2 diabetes and coronary heart disease." (PMID 31540515, 2019). "Herein, we demonstrate a streamlined approach to effectively screen and determine the function of secreted proteins in islets, and identified C1ql3 as a putative contributor to reduced insulin secretion in obesity, linking C1ql3 to an increased susceptibility to type 2 diabetes." (PMID 31300714, 2019). "Our results show that the HbA1c-associated miR-181a-2-3p, -146b-5p, -148a-3p, and -221-3p, and hsa-let-7a and miR-589-3p, were also independently and significantly (p < 0.05) associated with mRNA levels of the insulin signaling pathway and type 2 diabetes pathway genes." (PMID 31222113, 2019). "The polypeptide hormone insulin is essential for the maintenance of whole-body fuel homeostasis, and defects in insulin secretion and/or action are associated with the development of type 1 and type 2 diabetes." (PMID 30761839, 2019).